IL6 (interleukin 6)
Diseases named in the same sentence as IL6 in open-access papers (continued):
Sharing a sentence is not in itself a finding about the gene and the disease.
Hyponatremia (continued). "Therefore, our study cannot exclude the possibility that hyponatremia might be a surrogate marker of IL-6 secretion and degree of inflammatory response in the subgroup of SIAD patients." (PMID 33624101, 2021). "Additionally, there has been mounting evidence that the key pro-inflammatory cytokine IL-6 may serve as the missing link between states of systemic inflammation, a hallmark of post-operative patients, and the release of AVP and subsequent hyponatremia." (PMID 26553121, 2015). "Lipopolysaccharide (LPS) and inflammatory mediators (such as IL-1β, IL-6, and TNF-α) contribute to the pathogenesis of hyponatremia." (PMID 40636392, 2025). "Pro-inflammatory cytokines, such as interleukin-6 and TNF-alpha, trigger ADH release, leading to hyponatremia." (PMID 40282883, 2025). "Intracellular hypo-osmolality further activates the inflammasome with increased cytokine production of IL-1β and IL-6, contributing to a vicious cycle of more ADH and hyponatremia." (PMID 39797178, 2024). "Plasma IL-6 and TNF-α levels are significantly increased in IVIG-resistant children, which can explain the significant hyponatremia and can also serve as a predictor of IVIG-resistant KD." (PMID 36964445, 2023). "Inflammatory cytokines, such as interleukin (IL)-1β and IL-6, have been shown to induce activation of ADH, resulting in hyponatremia." (PMID 36556138, 2022). "In most patients, hyponatraemia is either euvolaemic due to SIADH, mainly owing to IL-6-induced AVP release, or hypovolaemic due to significant insensible fluid loss." (PMID 34370712, 2021). "Because IL-6 and IL-1β are all important cytokines in the pathogenesis of SLE both in animal models and human SLE21, 22, 23, 24, there is a possibility that increased these cytokines could be implicated in the pathogenesis of hyponatremia in the patients with SLE." (PMID 27193532, 2016). "Although the exact reasons for hyponatremia in patients with complicated appendicitis are not known, there is persuasive data to support the role of pro-inflammatory cytokines such as IL-6 in the non-osmotic release of antidiuretic hormone." (PMID 35884054, 2022). "The combination of antidiuresis effects of IL-6-mediated increases in ADH, infusion of IV NS, and increased oral water intake could all have contributed to the high rate of hyponatremia observed in this cohort." (PMID 31670650, 2020). "Meanwhile, the inflammation associated hyponatremia also occurred in non-malignant diseases, in which hyponatremia was correlated with neutrophil counts, CRP, IL-1β, and IL-6 levels." (PMID 33552948, 2020). "However, the mechanism of hyponatremia in complicated diverticulitis is likely related to the non-osmotic release of antidiuretic hormone (ADH), triggered by inflammatory cytokines such as interleukin-6." (PMID 40282883, 2025). "During cytokine storms, hyponatremia may result from the non-osmotic release of vasopressin driven by elevated IL-6 levels." (PMID 41440513, 2025). "Pro-inflammatory cytokines like interleukin-1β and IL-6 are believed to stimulate the secretion of arginine vasopressin, leading to the syndrome of inappropriate antidiuretic hormone (ADH) secretion (SIADH), which may contribute to hyponatremia in COVID-19." (PMID 39451561, 2024). "The pro-inflammatory cytokine IL-6, which is able to induce AVP release by central and peripheral mechanisms, may represent the common denominator of acute respiratory insufficiency and hyponatremia secondary to SIAD." (PMID 36831539, 2023). "IL-6 can induce non-osmotic release of vasopressin and secondary hyponatremia." (PMID 36297178, 2022). "Although the accurate etiology for hyponatremia in patients with complicated appendicitis is still not identified, there is persuasive data to support a role for pro-inflammatory cytokines, such as IL-6, IL-1β, etc., in the non-osmotic release of antidiuretic hormone (ADH)." (PMID 35884054, 2022).
Hyponatremia (continued). "Although no significant statistical correlation was found between hyponatremia and inflammatory markers like CRP, ESR, procalcitonin, or IL-6, hyponatremia was more common in severe cases and often approached critical levels." (PMID 39451561, 2024). "Patients who are malnourished and have inflammation-associated diseases may have elevated levels of proinflammatory cytokines like IL-1 Beta and IL-6, which can trigger non-osmotic ADH secretion and exacerbate hyponatremia." (PMID 40150087, 2025). "Increased levels of cytokines, such as IL-6, may directly stimulate non-osmotic release of arginine vasopressin (AVP), the predominant mechanism triggering hyponatremia in pediatric patients with MIS-C." (PMID 39451561, 2024). "The marked increase in plasma IL-6 and TNF-α in IVIG-resistant infants compared with IVIG-responsive patients may explain the significant hyponatremia in IVIG non-responders." (PMID 31921727, 2019). "Another possibility of SIADH-related hyponatremia in SARS-CoV-2 infection is due to a nonsuppressible vasopressin secretion even in the hypotonic state, stimulating kidney water reabsorption, mostly due to the central IL-6 effect, despite the low serum cortisol level and normal RAAS activity." (PMID 35960124, 2022).
esophageal squamous cell carcinoma (59 papers, 2013 to 2025). Esophageal squamous cell carcinoma (ESCC) is a type of esophageal carcinoma (EC) that can affect any part of the esophagus, but is usually located in the upper or middle third. "For example, our previous study demonstrated that the IL-6 -634G>C genetic polymorphism was associated with prognosis after surgery in advanced thoracic esophageal squamous cell carcinoma." (PMID 38469154, 2023). "In esophageal squamous cell carcinoma, IL-6 derived from cancer-associated fibroblasts plays the most important role in chemoresistance by upregulating the expression of C-X-C motif chemokine receptor 7 (CXCR7) via the STAT3/nuclear factor-κB (NF-kB) pathway." (PMID 33868231, 2021). "Another study demonstrated that CXCR7 expression had been upregulated by interleukin 6 (IL6) that is mainly derived from cancer-associated fibroblasts, contributing to chemoresistance in esophageal squamous cell carcinoma." (PMID 33363463, 2020). "Here we demonstrated that circulating CD11b+CD14+HLA-DR− cells were significantly increased in esophageal SCC patients compared with healthy people, and this was associated with the clinical stage, treatment response and circulating IL-6 levels." (PMID 25238263, 2014). "The aim of this study was to assess the significance of myeloid-derived suppressor cells (MDSCs) and their association with IL-6 in esophageal squamous cell carcinoma (SCC)." (PMID 25238263, 2014). "We demonstrated that positive IL-6 staining was significantly associated with a lower response rate after treatment in patients with esophageal SCC." (PMID 23561329, 2013). "As shown in previous studies, IL-6 and IL-1β are associated with the prognosis of esophageal SCC." (PMID 25238263, 2014). "Regarding clinical data, the expression of IL-6 was significantly associated with a lower rate of response to curative treatment in the 173 esophageal SCC patients, and a lower pathological complete response rate in the 55 patients who underwent surgical intervention." (PMID 23561329, 2013). "The aim of this study was to assess the significance of programmed cell death 1 ligand 1 (PD-L1) in esophageal squamous cell carcinoma (ESCC) and its association with IL-6 and radiation response." (PMID 26761210, 2016). "In conclusion, our findings demonstrate that elevated IL-6 not only correlates with the incidence of irAEs but also serves as a prognostic indicator for poorer outcomes in gastric adenocarcinoma and esophageal squamous cell carcinoma patients receiving ICIs." (PMID 40519900, 2025). "The activation of STAT3 by stimulation of IL-6 and IL-8 secreted from esophageal squamous cell carcinoma (ESCC) cells downregulates the activating receptors (NKp30 and NKG2D) on the surface of NK cells." (PMID 37501379, 2023). "High IL6 levels correlate with poor clinical outcomes in esophageal squamous cell carcinoma and invasive breast cancer." (PMID 35682546, 2022). "We previously reported that the NLR was relevant to IL-6 and MDSC levels, and that it was associated with poor prognosis in esophageal-SCC patients." (PMID 34578883, 2021). "IL-6 has been also shown to induce CD39 expression in tumor-infiltrating NK cells in esophageal squamous cell carcinoma, suggesting a broad IL-6-mediated mechanism regulating CD39 expression in several immune cells." (PMID 34360833, 2021). "And in esophageal squamous cell carcinoma, let-7 regulates IL-6/STAT3 pathway and is a significant determinant of response to chemotherapy." (PMID 32248842, 2020). "Further, IL-6 secreted by CAFs was reported to drive chemotherapy resistance in esophageal squamous cell carcinoma (ESCC)." (PMID 30927908, 2019). "And the upregulated expression of tumor suppressor let-7a is an extremely important determining factor in reacting to chemotherapy by regulating IL-6/STAT3 pathway in esophageal squamous cell carcinoma." (PMID 29156742, 2017).
esophageal squamous cell carcinoma (continued). "Consistent with that idea, B7-H4 facilitates cell proliferation by promoting a positive IL-6/STAT3 loopback pathway in esophageal squamous cell carcinoma." (PMID 27438152, 2016). "We previously observed that IL-6 was overexpressed in esophageal squamous cell carcinoma (ESCC), and their levels were positively correlated with disease progression." (PMID 26761210, 2016). "In summary, the levels of MDSC and IL-6 predicted the prognosis and treatment response of patients with esophageal SCC." (PMID 25238263, 2014). "In conclusion, the levels of MDSCs and IL-6 predicted the prognosis of patients with esophageal SCC." (PMID 25238263, 2014). "We reported previously that IL-6 correlated significantly with poor prognosis in esophageal SCC patients." (PMID 25238263, 2014). "We examined the percentage of CD11b+CD14+HLA-DR− myeloid cells and the levels of IL-6 in the peripheral blood of 50 patients with esophageal SCC and 12 healthy controls." (PMID 25238263, 2014). "The mean IL-6 level in esophageal SCC patients was 8.73±2.85 ng/ml, compared with 0.99±0.67 ng/ml in the healthy donors." (PMID 25238263, 2014). "The aim of this study was to highlight the significance of IL-6 in esophageal squamous cell carcinoma (SCC)." (PMID 23561329, 2013). "In human patients, gastric-esophageal reflux disease (GERD), Barrett’s esophagus (BE), esophageal squamous dysplasia and esophageal squamous cell carcinoma (ESCC) have been associated with increase in inflammatory cytokine stimuli such as IL-1β, IL-6, IL-8, IL-17 and TNFα4,6,9,15,48." (PMID 37543673, 2023). "Accumulating evidence has indicated that IL-6, a target of let-7a, confers radioresistance to different types of cancers and that serum IL-6 levels can be used to predict treatment responses and outcomes for patients with esophageal squamous cell carcinoma." (PMID 38114473, 2023). "Yujia Zheng also reported that tocilizumab prevented CD39 expression on NK cells induced by IL6 derived by esophageal squamous cell carcinoma cells, which suggested that tocilizumab may inhibit tumor growth via affecting NK cells." (PMID 33576874, 2021). "Our results are consistent with a recent study of esophageal squamous cell carcinoma (SCC) where IL-6 induced the accumulation of CD11b+CD14+HLA-DR− MDSC by stimulating STAT3 signal and its level in plasma samples was correlated with tumor progression and poor prognosis." (PMID 29100353, 2017). "Therefore, the present study was undertaken to discover the distribution and regulation of PD-L1 in esophageal SCC by IL-6 in the tumor microenvironment." (PMID 26761210, 2016). "The mean IL-6 level in esophageal SCC patients was 8.79±2.98 ng/ml." (PMID 26761210, 2016). "We have showed that IL-6 could be a significant predictor for clinical stage and prognosis of esophageal SCC." (PMID 26761210, 2016). "Moreover, we suggest inhibition of IL-6 as a potential strategy for the treatment of esophageal SCC." (PMID 25238263, 2014). "We further examined the predictive power of IL-6 for prognosis in esophageal SCC." (PMID 23561329, 2013). "Our data support the emerging notion that IL-6 and p-STAT3 are clinically significant predictors, and suggest that IL-6 may represent a suitable target for esophageal SCC treatment." (PMID 23561329, 2013). "In esophageal squamous cell carcinoma (ESCC), the activation of MDSCs is regulated by IL-6 and other signaling pathways mediated by aldehyde dehydrogenase." (PMID 40432130, 2025). "IL-6 secretion by esophageal squamous cell carcinoma (ESCC) CAFs, furthermore, increases upon coculture with tumor cells, activating STAT3/NF-κB signaling leading to an induction in CXCR7 expression enhancing chemoresistance to cisplatin." (PMID 35267539, 2022). "In esophageal squamous cell carcinoma (ESCC), IL-6 released by CAFs increased the chemoresistance of ESCC to cisplatin by increasing the chemokine receptor CXCR7 expression in tumor cells through the STAT3/NF-κB axis." (PMID 35814444, 2022).
esophageal squamous cell carcinoma (continued). "Research suggests that the JAK2/STAT3 pathway is involved in B7-H4-mediated IL-6 secretion in esophageal squamous cell carcinoma (ESCC) cells and enhances the growth and tumorigenicity of cells." (PMID 35505420, 2022). "Therefore, we hypothesized that IL-6 plays a critical role in the induction of MDSCs in patients with esophageal SCC." (PMID 25238263, 2014). "In humans, gastric-esophageal reflux disease (GERD), Barrett’s esophagus (BE), esophageal squamous dysplasia and esophageal squamous cell carcinoma (ESCC) have all been associated with a chronic enrichment of pro-inflammatory cytokines such as IL1-β, IL-6, IL-8, and TNFα4,13–15." (PMID 37543673, 2023). "In Esophageal Squamous Cell Carcinoma (ESCC), the increase of MDSCs is upregulated through IL-6 or other signaling pathways mediated by aldehyde dehydrogenase." (PMID 36131911, 2022). "A study in esophageal squamous cell carcinoma showed that inflammation or immune-related TLR4, IL-8, IL-6, and chemokine (C-X-C motif) ligand 2 (CXCL2) were increased upon PLCE1 suppression." (PMID 35054579, 2021). "CAF-secreted IL-6 stimulates the upregulation of CXCR7 through STAT3/NFκB signaling, promoting resistance of esophageal squamous cell carcinoma cells against cisplatin and 5-FU." (PMID 33363463, 2020). "Recent research reported that tumor cell-secreted IL-6 and IL-8 impair the activity and function of NK cells via STAT3 signaling, and contribute to esophageal squamous cell carcinoma malignancy." (PMID 32973887, 2020). "Whereas STAT3 is not described as a direct substrate, inhibition of GSK3β after stimulation with IFN-γ, IL-6, or IFN-α reduces the phosphorylation of STAT3 on Y705, and GSK3β modifies STAT3 phosphorylation in esophageal squamous cell carcinoma." (PMID 31862381, 2020). "IL-6 produced by activated fibroblasts induces tumor angiogenesis and promotes chemoresistance via CXCR7 in esophageal squamous cell carcinoma." (PMID 31998637, 2019). "We assessed the relationship between plasma IL-6 levels and tumor progression by assessing MDSC levels in clinical patients with esophageal SCC and in 4-NQO-treated mice." (PMID 25238263, 2014). "The study found that IL-6 could induce ENTPD1 expression on tumor-infiltrating NK cells, which predicted a poor prognosis in esophageal squamous cell carcinoma." (PMID 34465393, 2021). "Likewise, increase of inflammation was also detected shortly after Photofrin-PDT, as indicated by elevated levels of serum IL-6, a pro-inflammatory cytokine, in patients with esophageal squamous cell carcinoma (ESCC) at one week after treatment, but this declined soon after two weeks." (PMID 31991650, 2020). "However, the role of IL-6 on ICIs treatment for gastric adenocarcinoma (GAC) and esophageal squamous cell carcinoma (ESCC) — two of the most prevalent and aggressive upper gastrointestinal malignancies — remains unclear." (PMID 40519900, 2025). "In addition, IL6 release due to chronic inflammation is known to induce the expression of CD39, and IL6-induced CD39 expression on tumor-infiltrating NK cells has been reported to predict poor prognosis in esophageal squamous cell carcinoma." (PMID 38592450, 2024). "Furthermore, in esophageal squamous cell carcinoma (ESCC), CAF-derived exosomal miR-21 and IL-6 synergistically promoted the generation of monocytic myeloid-derived suppressor cells (M-MDSCs) via activating STAT3 by IL-6 in an autocrine pathway." (PMID 39684264, 2024). "T. forsythia can induce pro-inflammatory cytokines such as IL-1β and IL-6 by CD4 + T helper cells and TNF-α in esophageal squamous cell carcinoma (ESCC)." (PMID 35847109, 2022). "For example; in esophageal squamous cell carcinoma abrogation of JAK-STAT3 signaling downregulates NF-κB signaling, in head and neck squamous cell carcinoma interfering with NF-κB reduced STAT3 signaling and in brain pericytes STAT3 cooperates with NF-κB to induce IL-6 production." (PMID 35769477, 2022).
esophageal squamous cell carcinoma (continued). "In esophageal squamous cell carcinoma (ESCC), differentially methylated CpG sites between cancer tissue and healthy tissue were found in genes in the IL10 signaling pathway; IL-6 was found to be hypomethylated, while IL-1α was found to be hypermethylated." (PMID 34901003, 2021). "Furthermore, the human esophageal SCC cell line CE81T was selected for cellular and animal experiments to investigate changes in tumor behavior and treatment response after manipulation of IL-6 expression." (PMID 23561329, 2013).